SERTM2 (serine rich and transmembrane domain containing 2)
Description:
Promotes GDNF-mediated spinal cord motor neuron subtype specification, ensuring the maintenance of ETV4-expressing motor neurons. Affects the resting membrane potential and excitability of motor neurons.
Synonyms: CARDEL; DKFZp686D0853; LINC00890
Gene: Protein-coding gene on chromosome X (111,511,645 to 111,522,399, forward strand). Ensembl gene ENSG00000260802.
Subcellular location: Cytoplasm; Cell membrane
Gene Ontology:
Cellular component: plasma membrane; cytoplasm
Homologues: Orthologues: chimpanzee SERTM2 (99% identical), pig SERTM2 (94% identical), rabbit SERTM2 (93% identical), dog SERTM2 (92% identical), rat Sertm2 (92% identical), mouse Sertm2 (91% identical), guinea pig SERTM2 (89% identical).
Diseases named in the same sentence as SERTM2 in open-access papers:
SERTM2 is named in the same sentence as 5 diseases in open-access papers, as found by Europe PMC text mining. Sharing a sentence is not in itself a finding about the gene and the disease. The quoted sentences say what the papers report.
melanoma (1 paper, 2025). A malignant, usually aggressive tumor composed of atypical, neoplastic melanocytes. "SERTM2 gene alterations are frequently observed in melanoma, suggesting a potential role in tumor progression and immune evasion." (PMID 41574107, 2025).
SERTM2 also shares sentences with these, for which no sentence is quoted: tumor (2 papers); cancer (1); hypertrophic cardiomyopathy (1); skin cutaneous melanoma (1).